AFF2 (ALF transcription elongation factor 2)
Description:
RNA-binding protein. Might be involved in alternative splicing regulation through an interaction with G-quartet RNA structure.
Synonyms: FMR2P; FMR2; OX19; FRAXE; MRX2; XLID109
Tractability: PROTAC: ubiquitination databases record sites on it.
Gene: Protein-coding gene on chromosome X (148,500,617 to 149,000,663, forward strand). Ensembl gene ENSG00000155966.
Subcellular location: Nucleus speckle
Gene Ontology:
Molecular function: G-quadruplex RNA binding; transcription coregulator activity
Biological process: nuclear speck organization; regulation of gene expression; regulation of RNA splicing; brain development; DNA-templated transcription elongation; nervous system process; regulation of DNA-templated transcription
Cellular component: nuclear speck; super elongation complex; nucleus
Gene-disease validity (ClinGen):
ClinGen rates the evidence that AFF2 causes each of these diseases.
non-syndromic X-linked intellectual disability (X-linked): Definitive. Nonspecific X-linked intellectual deficiencies (MRX) belong to the family of sex-linked intellectual deficiencies (XLMR).
Homologues: Orthologues: chimpanzee AFF2 (99% identical), macaque AFF2 (98% identical), pig AFF2 (91% identical), dog AFF2 (90% identical), guinea pig AFF2 (89% identical), rabbit AFF2 (86% identical), mouse Aff2 (86% identical), rat Aff2 (86% identical), tropical clawed frog aff2 (55% identical), zebrafish aff2 (50% identical), Drosophila melanogaster lilli (20% identical). Paralogues in human: AFF3 (37% identical), AFF4 (33% identical), AFF1 (28% identical).
Diseases named in the same sentence as AFF2 in open-access papers:
AFF2 is named in the same sentence as 75 diseases in open-access papers, as found by Europe PMC text mining. Sharing a sentence is not in itself a finding about the gene and the disease. The quoted sentences say what the papers report.
Intellectual disability (22 papers, 2006 to 2024). "Further analysis revealed that the AFF2 mutations associated with partial epilepsy in this study were all missense, in contrast, intellectual disability-associated mutations were genomic rearrangements and CCG repeat expansion mostly." (PMID 35431806, 2022). "Previously, intellectual disability-associated AFF2 mutations were genomic rearrangements and CCG repeat expansion mutations mostly, whereas the mutations associated with partial epilepsy were all missense." (PMID 35431806, 2022). "Silencing of AFF2 caused by this CCG trinucleotide repeat expansion results in mild intellectual disability named fragile XE or FRAXE syndrome." (PMID 27811963, 2016). "The study indicated that missense AFF2 mutations could also lead to other phenotypes such as intellectual disability, possibly associated with the molecular sub-regional location." (PMID 35431806, 2022). "Indeed, the X-linked gene AFF2 has been found in patients with fragile X E (FRAXE) intellectual disability, while the gene encoding the serine/threonine-protein kinase BRSK2 was recently detected in individuals with developmental and intellectual disability." (PMID 34834471, 2021). "AFF2 encodes FRAXE-associated mental retardation protein (FMR2) within which small changes were found in patients with intellectual disability and developmental delay, and significantly more frequent rare variants were detected in AFF2 by massively parallel sequencing of males with ASD." (PMID 23227143, 2012). "Over 100 X-linked intellectual disability genes have been identified, with triplet repeat expansions at the FMR1 (FRAXA) and AFF2 (FRAXE) genes being the causative agent in two of them." (PMID 34282157, 2021). "There was also overlap for genes involved in intellectual disabilities, including AFF2, AIFM1, CA8, EEF1A2, MLC1, and XYLT1, but statistically the overlap is not significant." (PMID 32393163, 2020). "AFF2 is also known as FMR2 (fragile mental retardation 2); loss of its expression due to a CCG expansion in the 5′UTR results in a mild to borderline intellectual disability, fragile XE syndrome." (PMID 31784536, 2019). "AFF2 is a transcriptional regulator that is best known in the germline setting as a cause of intellectual disability, yet AFF2 itself has never previously been implicated in cancer." (PMID 38429827, 2024). "Second, previous studies revealed that some of the AFF2 mutations associated with intellectual disability were CCG repeat expansion, which were not included in the present study." (PMID 35431806, 2022). "Five missense mutations of AFF2 were identified in five unrelated individuals of partial epilepsy without intellectual disability or other developmental abnormalities." (PMID 35431806, 2022). "Previous studies showed that intellectual disability associated AFF2 mutations were genomic rearrangements and CCG repeat expansion mostly, suggesting a pathogenic role of loss-of-function of AFF2 in intellectual disability." (PMID 35431806, 2022). "This study identified five missense AFF2 mutations in five unrelated males with partial epilepsy and antecedent febrile seizures without intellectual disability or other developmental abnormalities." (PMID 35431806, 2022). "Third, a previous study reported that a missense mutation of AFF2 was identified in a 6-year-old boy with focal epilepsy and moderate intellectual disability, but without febrile seizures." (PMID 35431806, 2022). "Five hemizygous missense AFF2 mutations were identified in five males with partial epilepsy and antecedent febrile seizures without intellectual disability or other developmental abnormalities." (PMID 35431806, 2022). "Simultaneous deletion of both FMR1 and AFF2 in males results in severe intellectual disability." (PMID 30264515, 2018). "AFF2 is silenced in cases of Fragile XE (FRAXE) intellectual disability." (PMID 26214578, 2015).
Intellectual disability (continued). "In conclusion, laboratories performing molecular genetic studies of idiopathic intellectual disability would benefit from the implementation of this methodology, which enables a widened scope of detection of the mutational hotspot regions of FMR1, AFF2 and ARX genes in a single initial assay." (PMID 23914978, 2013). "AFF2, DOCK8, NIPBL, and RPS6KA3 were implicated in intellectual disability." (PMID 23227143, 2012). "The literature review showed that variants affecting the AFF2 gene are mainly associated with the Intellectual Developmental Disorder X-Linked 109 (FRAXE, OMIM, #309548), a rare type of intellectual disability without well-characterized specific phenotypic abnormalities." (PMID 39553472, 2024).
FRAXE syndrome (9 papers, 2013 to 2024). "We subsequently compare the clinical features of the reported individuals with those of FRAXE syndrome, AFF2 variants and CdLS." (PMID 39553472, 2024). "Clinical features of the patient (II-1), his mother (I-2) and his maternal aunt affected (I-3) compared with the clinical features of FRAXE syndrome, copy number variants affecting the AFF2 gene and Cornelia de Lange syndrome." (PMID 39553472, 2024). "Fragile‐X syndrome (FMR1) and FRAXE syndrome (AFF2) are well‐known causes of X‐linked recessive intellectual disability." (PMID 30264515, 2018). "The trinucleotide repeat expansion of CCG at 5′ untranslated region (UTR) of AFF2 causes fragile XE syndrome (FRAXE)." (PMID 30249282, 2018). "Deletion of FMR1 and AFF2 has been shown to cause fragile X syndrome and probably FRAXE‐syndrome." (PMID 30264515, 2018). "Interestingly, the CCG repeat expansion occurring at the 5′end of the FMR2 (AFF2) gene, which is associated with FRAXE syndrome, is shown to exhibit RAN translation in the premutated state in the Drosophila model." (PMID 33854084, 2021). "The silencing of the AFF2 gene can lead to Fragile XE syndrome." (PMID 25351872, 2015). "Therefore, all these features suggest that the underlying clinical features in patients carrying intragenic variants in the AFF2 gene would not be explained by the clinical picture described for FRAXE syndrome." (PMID 39553472, 2024). "However, the literature reports other intragenic variants of the AFF2 gene associated with clinical features that do not involve FRAXE syndrome." (PMID 39553472, 2024).
autism (7 papers, 2014 to 2022). Persistent deficits in social interaction and communication and interaction as well as a markedly restricted repertoire of activity and interest as well as repetitive patterns of behavior. "Partial AFF2 deletions, especially smaller deletions, are usually associated with a milder phenotype or autism, whereas complete loss of gene function causes FRAXE." (PMID 39817275, 2022). "Rare pathogenic variants in the AFF2 gene have been identified in patients with autism and attention deficit hyperactivity disorders as well as with X-linked intellectual disability and developmental and speech delay." (PMID 30249282, 2018). "Among highly expressed genes in Autism and other disorders, I also found AFF2 and BRSK2, both with score 1 in SFARI and reportedly critical for neurodevelopment." (PMID 34834471, 2021). "Simultaneous deletion of both FMR1 and AFF2 in males results in severe ID and variable other features including hypotonia, epilepsy, obesity, and autism." (PMID 30264515, 2018).
autism spectrum disorder (7 papers, 2014 to 2023). A spectrum of developmental disorders that includes autism, and Asperger syndrome. "AFF2 mutations were associated with X-linked intellectual developmental disorder-109 and in males with autism spectrum disorder (ASD)." (PMID 35431806, 2022). "Besides, the AFF2 gene has been reported to be associated with autism spectrum disorder, neuroticism, and educational attainment." (PMID 38035272, 2023). "Moreover, rare missense variations in the highly evolutionary conserved sites of the AFF2 gene might be associated with autism spectrum disorder." (PMID 24763282, 2014). "In addition, a significant enrichment among the nominal DEGs for genes implicated in autism spectrum disorder (ASD) was found (e.g., AFF2, DNER, DPP6, DPP10, RELN, CACNA1C), as well as several that are strong candidate genes for the development of eye problems found in LS, including glaucoma." (PMID 32393163, 2020).
fragile X syndrome (6 papers, 2018 to 2024). A genetic syndrome caused by mutations in the FMR1 gene which is responsible for the expression of the fragile X mental retardation 1 protein. "Here, a total of 30 (2.1%) GDD/ID children presented both AFF2 gene mutation and Fragile X syndrome." (PMID 39817275, 2022). "In addition, the incidence of Fragile X syndrome in 488 children with identified pathogenic mutations was lower than those of AFF2 (3.6%) and HUWEI (3.0%) in male GDD/ID children." (PMID 39817275, 2022). "A rare pathogenic variant in the AFF2 gene has been identified in patients with fragile X syndrome." (PMID 30249282, 2018). "Newborn screening of AFF2 gene and Fragile X syndrome is recommended for early diagnosis and intervention of potential genetic diseases, especially for those high-risk families." (PMID 39817275, 2022).
breast carcinoma (3 papers, 2014 to 2021). "For instance, circ-AFF2 might sponge miR-638, which was previously shown to induce drug resistance in human breast cancer, thereby reduced drug resistance and improved prognosis in MM patients." (PMID 31948430, 2020).
epilepsy (3 papers, 2018 to 2024). A brain disorder characterized by episodes of abnormally increased neuronal discharge resulting in transient episodes of sensory or motor neurological dysfunction, or psychic dysfunction. "Epileptic seizures were also observed in patients with genomic rearrangements, suggesting that loss-of-function of AFF2 would be potentially associated with epilepsy." (PMID 35431806, 2022). "Further analysis revealed that missense AFF2 mutations with epilepsy in this study mainly fell into the regions from the N-terminal to the NLS1, whereas the missense mutations with ASD mainly fell in the regions from the NLS1 to the C-terminal." (PMID 35431806, 2022). "Missense AFF2 mutations associated with epilepsy fell into the regions from N-terminal to the nuclear localization signal 1 (NLS1), while ASD-associated missense mutations fell in the regions from NLS1 to C-terminal." (PMID 35431806, 2022). "AFF2 mutations were identified in five unrelated male epilepsy patients with focal seizures and/or focal discharges, ranging in age from 5 to 27 years." (PMID 35431806, 2022). "Apart from epilepsy, missense AFF2 mutations have also been identified in patients with ASD." (PMID 35431806, 2022). "The relationship between AFF2 and epilepsy has not been defined." (PMID 35431806, 2022).
head and neck cancer (3 papers, 2023 to 2025). A primary or metastatic malignant neoplasm affecting the head and neck. "We present five novel head and neck carcinomas harboring AFF2 rearrangements involving previously unreported fusion partners." (PMID 40494991, 2025).
premature ovarian failure (3 papers, 2014 to 2019). "In addition, three genes (DIAPH2, AFF2, POF1B) were involved in functions related to premature ovarian failure." (PMID 24422716, 2014).
sinonasal carcinomas (3 papers, 2022 to 2025). "Follow-up imaging in July 2024, using PET-CT, demonstrated complete metabolic remission of the DEK::AFF2 fusion-associated sinonasal carcinoma." (PMID 40688086, 2025). "The presented cases underscore the formidable clinical challenges posed by DEK::AFF2 fusion-associated sinonasal carcinomas, characterized by aggressive local invasion and a high propensity for recurrence." (PMID 40688086, 2025). "However, the deceptively bland histological features raise critical challenges in distinguishing DEK::AFF2 fusion-associated sinonasal carcinomas from inverted sinonasal papillomas based solely on morphology." (PMID 40688086, 2025). "With the recognition of a larger cohort of skull base and sinonasal carcinomas that harbor DEK::AFF2 fusions and confirmation that a subset lacks other known oncogenic mutations, our study solidifies the role of this unique genetic event as the key driver of these tumors." (PMID 38429827, 2024). "These include, among others, the identification of a subset of sinonasal carcinomas associated with HPV infection, the identification of a subset of squamous cell carcinomas with EGFR alterations, and of rare variants with chromosomal translocations (DEK::AFF2, ETV6::NTRK and others)." (PMID 35326613, 2022).
squamous cell carcinoma (3 papers, 2022 to 2025). A carcinoma arising from squamous epithelial cells. "DEK::AFF2 fusion squamous cell carcinoma (SCC) is a rare and aggressive subtype of non-keratinizing SCC." (PMID 40299135, 2025).
X-linked intellectual disability (3 papers, 2018 to 2023). An X-linked intellectual deficiency in which not enough information is known, reported or published to indicate whether a gene causes non-syndromic or syndromic presentations. "The expansion of CCG trinucleotide in the AFF2 gene causes a form of X-linked intellectual disability (ID) related to Fragile site E (FRAXE) at Xq28." (PMID 39817275, 2022). "CCG repeat expansions in the AFF2 gene are associated with X-linked intellectual disability." (PMID 38035272, 2023).
acute lymphoblastic leukemia (2 papers, 2014 to 2015). Leukemia with an acute onset, characterized by the presence of lymphoblasts in the bone marrow and the peripheral blood. "The AFF (AF4/FMR2) family of genes includes four members: AFF1 (or AF4, acute lymphoblastic leukemia-1 fused gene from chromosome 4), AFF2 (or FMR2, Fragile X mental retardation 2), AFF3 and AFF4 (or AF5Q31, acute lymphoblastic leukemia-fused gene from 5q31)." (PMID 26214578, 2015). "The AFF (AF4 (ALL1 (acute lymphoblastic leukemias)-fused gene from chromosome 4)/FMR2 (fragile X mental retardation 2)) family of genes includes four members: AFF1/AF4, AFF2/FMR2, AFF3/LAF4 and AFF4/AF5q31." (PMID 25268620, 2014).
inverted papilloma (2 papers, 2025). An endophytic benign papillary epithelial neoplasm that results from the invagination and proliferation of epithelial cells in the underlying stroma. "In both cases, diagnostic confirmation of DEK::AFF2 fusion was significantly delayed, primarily due to initial misclassification as inverted papilloma, a pitfall commonly encountered given the overlapping morphological features." (PMID 40688086, 2025). "Additionally, a 52-year-old non-smoking female, initially diagnosed with inverted papilloma in the ethmoid sinus, experienced multiple recurrences in the sinonasl tract over 24 years, ultimately presenting with a tracheal mass harboring DEK::AFF2 fusion." (PMID 40299135, 2025).
macrosomia (2 papers, 2016 to 2024). "AFF2 gene duplications have been previously reported in the literature and have recently been implicated in auditory processing, emotional impairment and macrosomia." (PMID 27034718, 2016).
NUT carcinoma (2 papers, 2023 to 2025). "In recent years, multiple molecularly defined entities have emerged in head and neck pathology, especially among sinonasal squamous and basaloid carcinomas, including NUT carcinoma, SWI/SNF-deficient carcinoma, and DEK::AFF2 carcinoma." (PMID 40494991, 2025). "For example, carcinomas comprise conventional squamous cell carcinomas, NUT carcinomas, DEK::AFF2 carcinomas, EBV- and HPV-associated carcinomas, undifferentiated as well as SWI/SNF complex deficient sinonasal carcinomas, highlighting the variety of different morphologies and molecular pathogeneses." (PMID 37118352, 2023). "We report the case of a 32-year-old patient with an unusual NUT carcinoma originating in the maxillary sinus, which showed extensive well-differentiated, papillary squamous morphology, similar to the spectrum of the recently described DEK::AFF2 fusion-associated carcinoma." (PMID 37118352, 2023). "Surprisingly, no DEK::AFF2, but a NUT::NSD3 gene fusion was detected, leading to the diagnosis of a NUT carcinoma." (PMID 37118352, 2023).
partial epilepsy (2 papers, 2022 to 2023). "This study suggests that AFF2 is potentially a candidate causative gene of X-link partial epilepsy with antecedent febrile seizures." (PMID 35431806, 2022). "Five hemizygous missense AFF2 variants were identified in five unrelated individuals with partial epilepsy, including c.230A > T/p.N77I, c.391C > T/p.H131Y, c.1540C > T/p.R514C, c.2009G > A/p.R670H, and c.2074C > G/p.P692A." (PMID 35431806, 2022). "AFF2 is potentially a candidate causative gene of X-link partial epilepsy with antecedent febrile seizures." (PMID 35431806, 2022). "In the present study, five novel missense AFF2 mutations were identified in five male individuals with partial epilepsy and antecedent febrile seizures." (PMID 35431806, 2022). "AFF2 is ubiquitously expressed in multiple human brain tissues and is more abundant in the frontal cortex, anterior cingulate cortex, hippocampus, and the amygdala, which may provide an anatomical basis for the phenotype of partial epilepsy." (PMID 35431806, 2022).
rheumatoid arthritis (2 papers, 2021 to 2022). A chronic, systemic autoimmune disorder characterized by inflammation in the synovial membranes and articular surfaces. "The purpose of this study is to explore the function and mechanism of circRNA fragile mental retardation 2 (circ-AFF2) in the processes of rheumatoid arthritis fibroblast-like synoviocytes (RAFLSs)." (PMID 33653372, 2021). "Circ_0003972, circ-AFF2, circ_0003353, and circ_0088194 are highly expressed in RA patients and fibroblast-like synoviocytes of rheumatoid arthritis (HFLS-RA) cells, circ_0008360, and circ_0130438 expressions were down-regulated." (PMID 36278188, 2022).
Airway obstruction (1 paper, 2025). Obstruction of conducting airways of the lung. "We describe the first documented case of primary laryngeal SCC harboring a DEK::AFF2 fusion in a 64-year-old female who presented with progressive hoarseness and airway obstruction." (PMID 40299135, 2025).